FGFR4 (fibroblast growth factor receptor 4)
Diseases named in the same sentence as FGFR4 in open-access papers (continued):
Sharing a sentence is not in itself a finding about the gene and the disease.
prostate carcinoma (continued). "In this study, we investigated whether the polymorphisms of FGFR4 influence the biochemical recurrence of prostate cancer in Chinese men after radical prostatectomy." (PMID 27640814, 2016). "Finally, the FGFR4 Gly388Arg polymorphism has been shown to be a potential marker for prostate cancer development and progression." (PMID 25894690, 2015). "Similarly, the FGFR4 Arg388 SNP variant which is found in most prostate cancer, has been reported not only to protect FGFR from lysosomal degradation, but also to sustain receptor phosphorylation." (PMID 23900974, 2013). "Moreover, among the four articles, three mentioned the association between FGFR4 Gly388Arg polymorphism and progression of prostate cancer." (PMID 21349172, 2011). "Hence, we carried out a meta-analysis of all eligible case-control studies to derive a more precise estimation of the association of FGFR4 Gly388Arg polymorphism with prostate cancer." (PMID 21349172, 2011). "Our meta-analysis showed the evidence that FGFR4 Arg388 allele was associated with an increased risk of prostate cancer development and progression, suggesting that FGFR4 Gly388Arg polymorphism could be a marker for prostate cancer development and progression." (PMID 21349172, 2011). "In another investigation, the researchers showed that expression of the FGFR4 Arg388 protein activated the extracellular signal-related kinase pathway with subsequent expression of several genes which were associated with the aggressive form of prostate cancer, (Rev1-1)." (PMID 33017009, 2020). "This meta-analysis showed the evidence that FGFR4 Gly388Arg polymorphism was associated with an increased risk of prostate cancer development and progression, suggesting that FGFR4 Gly388Arg polymorphism could be a marker for prostate cancer development and progression." (PMID 21349172, 2011). "In addition, when concerning tumor stage and FGFR4 Gly388Arg polymorphism, patients with prostate cancer with Arg/Arg genotype had a 1.34-fold increased risk of advanced or metastatic prostate cancer (95% CI: 1.03-1.74) compared with the Gly/Gly+Gly/Arg genotype." (PMID 21349172, 2011). "The expression of FGFR4 is increased in more advanced cases, which indicates that up-regulation of FGFR4 is related to a poor prognosis of prostate cancer." (PMID 33446698, 2021). "We also utilized an online database to assess the expression of FGFR4 in prostate cancer participants and normal controls." (PMID 33446698, 2021). "In order to demonstrate the expression of FGFR4 in prostate cancer tissues, we applied IHS to evaluate its expression among prostate cancer patients at our centers." (PMID 33446698, 2021). "In summary, our work demonstrated that BCR-free survival significantly varied in patients with prostate cancer with different FGFR4 rs351855 genotypes." (PMID 27640814, 2016). "Consistent with this, the levels of SEF is downregulated, whereas FGF2, FGF8, and FGFR4 levels are upregulated in aggressive prostate cancer specimens." (PMID 23900974, 2013). "Recently, FGFR4 was found to be more abundantly expressed in malignant than benign prostate cells and in vitro suppression of FGFR4 expression effectively blocked prostate cancer proliferation and invasion." (PMID 21349172, 2011). "Since previous research has implicated FGFR4 in prostate cancer progression, we sought to examine the effect of FGFR4 activation on NFκB signaling in DU145 prostate cancer cells, known to express high levels of endogenous FGFR4." (PMID 21203561, 2010). "FGF19 stimulation of endogenous FGFR4 in TNFα-treated DU145 prostate cancer cells also leads to a decrease in IKKβ activity, concomitant reduction in NFκB nuclear localization, and reduced apoptosis." (PMID 21203561, 2010). "High-grade prostate cancer also had significantly higher expression of FGFR4 protein than moderate-grade prostate cancer (P<0.005)." (PMID 15655558, 2005).
prostate carcinoma (continued). "First, we examined for abnormal expression of FGFR3 and FGFR4 in clinical prostate cancer specimens." (PMID 15655558, 2005). "In this group, patients with low to moderate staining for FGFR4 had a mean survival time of 64.6 months, compared to 45.5 months for patients with prostate cancer expressing high levels of FGFR4." (PMID 15655558, 2005). "Patients with high-grade prostate cancer and low to moderate staining had a mean survival of 54.4 months compared to 45.5 months for people with high FGFR4 expression in high-grade prostate cancer." (PMID 15655558, 2005). "In summary, we presented evidence for clinical significant FGFR4 overexpression in prostate cancer, and further validated the potential of targeting the FGFR system for treatment in conjunction with current available modalities." (PMID 15655558, 2005). "The prostate is known to express FGFR1, 2 and 3, while FGFR4 has only been detected at low levels in prostate cancer cell lines." (PMID 12778074, 2003). "We further utilized TCGA samples to assess the expression of FGFR4 in prostate cancer participants." (PMID 33446698, 2021). "FGFR4 expression is elevated in prostate cancer compared with that in the control." (PMID 33446698, 2021). "IHS analysis indicated that FGFR4 expression is increased in advanced prostate cancer." (PMID 33446698, 2021). "The FGFR4 expression was elevated in prostate cancer compared with that in the control group." (PMID 33446698, 2021). "Moreover, strong expression of FGFR4 in prostate cancer cells, as assessed by immunohistochemistry, is significantly associated with increased clinical stage and tumor grade and decreased patient survival." (PMID 21349172, 2011). "Up-regulation of FGFR4 may be related to a poor prognosis in prostate cancer." (PMID 33446698, 2021). "Hence, FGFR4 rs351855 may be a novel independent prognostic of BCR of Chinese patients with prostate cancer after radical prostatectomy." (PMID 27640814, 2016). "In prostate cancer, FGFR1 and FGFR4 as well as the ligands FGF-1, FGF-2, FGF-6, FGF-8, FGF-9, and FGF-17 are all known to be over-expressed." (PMID 22078327, 2011). "Fibroblast growth factor receptor 4 (FGFR4) displays multiple biological activities, including mitogenic and angiogenic activity, and plays important roles in the etiology and progression of prostate cancer." (PMID 21349172, 2011). "Furthermore, we demonstrate that endogenous FGFR4 and IKKβ proteins interact in the DU145 prostate cancer cell line." (PMID 21203561, 2010). "FGFR4 immunoreactivity was compared between BPH and various grades of prostate cancer." (PMID 15655558, 2005).
gastric cancer (23 papers, 2014 to 2026). A primary or metastatic malignant neoplasm involving the stomach. "It has been demonstrated that FGFR4 is highly expressed in gastric cancer tissues, and this high expression is associated with a poor prognosis." (PMID 38540215, 2024). "Yanwei Ye and colleagues investigated the role of the Arg388 variant of fibroblast growth factor receptor 4 (FGFR4) in gastric cancer (GC)." (PMID 39309860, 2024). "Accordingly, we searched for activating FGFR4 mutations of the tyrosine kinase domain in 83 gastric cancer tissue specimens." (PMID 31601997, 2019). "Here, we describe the identification of a novel oncogenic mutation of FGFR4 (G636C) in gastric cancer." (PMID 31601997, 2019). "We therefore hypothesized that FGFR4 plays an important role in gastric cancer and that mutations that activate the protein tyrosine kinase activity of FGFR4 promote an aggressive phenotype." (PMID 31601997, 2019). "Here, we identified a novel oncogenic mutation (G636C) of FGFR4 in a primary gastric cancer." (PMID 31601997, 2019). "Additionally, high expression levels of FGFR1, FGFR2, or FGFR4 are associated with tumor progression and poor survival in patients with gastric cancer." (PMID 26993773, 2016). "Showing promise in RMS treatment, these mAbs also hold potential for other cancers with high FGFR4 expression, such as prostate, melanoma, lung, breast, colorectal, and gastric cancers." (PMID 41328353, 2026). "In gastric cancer, overexpressed fibroblast growth factor receptor 4 (FGFR4) forms a complex with p62 and KEAP1, which blocks KEAP1-mediated NRF2 ubiquitination and degradation." (PMID 40227215, 2025). "Xing Zhang and colleagues determined the molecular relationships among H. pylori, inflammatory responses, and FGFR4 in gastric cancer pathology." (PMID 39309860, 2024). "Downregulation of miR-491-5p induces EMT by regulating SNAIL and FGFR4, thereby promoting gastric cancer metastasis." (PMID 39668817, 2024). "In colorectal cancer models, which share similar pathological environments and treatment approaches with gastric cancer, FGFR4 silencing has been shown to induce poly ADP-ribose polymerase-1 (PARP) cleavage." (PMID 39309860, 2024). "Immunotherapy such as anti-PDL1 therapy has been shown to have more effect in FGFR wild-type tumors in bladder cancer cell lines while less effects from immunotherapy were observed in FGFR4-overexpressed gastric cancer cells." (PMID 38255923, 2024). "Helicobacter pylori infection increases the expression of FGFR4 in gastric cancer cells through activation of the STAT3 pathway by FGF19, and STAT3 binds directly to the FGFR4 promoter, forming a feed‐forward response loop." (PMID 37750089, 2023). "The expression of FGFR2 and FGFR4 was higher in human stomach cancers than in normal tissues, according to the GEPIA and TCGA datasets." (PMID 36147913, 2022). "High FGFR4 protein overexpression has been correlated with lymph node metastasis in triple-negative breast cancers and gastric cancer." (PMID 36142417, 2022). "Researchers have reported that there was not any significant difference between different genotypes of FGFR4 in gastric cancer." (PMID 33017009, 2020). "Considering the current exploratory attempts to use PARP inhibitors in gastric cancer treatment, the addition of a PARP inhibitor (such as olaparib) to oxaliplatin chemotherapy for FGFR4-Arg388 gastric cancer patients is worth investigating." (PMID 39309860, 2024). "FGFR4 is member of FGFR family with oncogenic potential in various solid neoplasms including, among others, stomach cancers." (PMID 37945798, 2024). "Repeating this analysis in a second independent cohort of 20 pairs of gastric cancer samples re-identified MET and FGFR4 as upregulated in GC samples (left)." (PMID 33482911, 2021). "For instance, miR-491-5p is down-regulated in gastric cancer tissues, and it represses epithelial-mesenchymal transformation of gastric cancer cells by combining 3′-UTRs of SNAIL and FGFR4." (PMID 33097010, 2020).
gastric cancer (continued). "FGFR4 is widely known as a star target in HCC and gastric carcinoma." (PMID 41213916, 2025).
liver cancer (20 papers, 2012 to 2026). An epithelial or non-epithelial malignant neoplasm that arises from the liver. "First, FGF15/19 activation of FGFR4 has been associated with abnormal hepatocytes proliferation and increased risk of liver cancer." (PMID 36586437, 2023). "FGF19 and its receptor FGFR4 are oncogenic drivers of liver cancer and associated with a poor prognosis." (PMID 33809909, 2021). "FGFR1S602F was reported in only one case of melanomaand FGFR2, and FGFR4 mutations were found in 4/231 (1.7%) and 1/231 (0.4%) liver cancer samples, respectively." (PMID 27384874, 2016). "The increased expression of FGFR4 in a subset of liver tumors suggests that it may represent an attractive target for the treatment of liver cancer in a diagnostic-selected patient population." (PMID 22615798, 2012). "For example, we found FGFR4 expression to be significantly increased in a subset of primary liver tumors, suggesting that FGFR4 may represent an attractive target for the treatment of liver cancer in a diagnostic-selected patient population." (PMID 22615798, 2012). "FGFR4 targeting agents are an area of high interest in liver cancer, where a subset of patients exhibits an amplification of FGF19, a unique FGFR4 ligand." (PMID 40731412, 2025). "U3-1784, a novel FGFR4 targeting antibody, exerts strong antitumor effects specific to liver cancer cells overexpressing FGF19." (PMID 34576070, 2021). "In fact, since the occurrence and development of liver cancer are more dependent on FGFR4, the current FGFR4 inhibitors are mainly aimed at the treatment of HCC." (PMID 33981224, 2021). "50% of cholangiocarcinoma and 31.6% of liver cancer patients displayed FGFR4 overexpression concerning cancer initiation and progression." (PMID 33655556, 2021). "Recently, the selective FGFR4 inhibitor fisogatinib has presented some promising results in phase I/II clinical trials and brought new therapeutic opportunities to liver cancer." (PMID 34522226, 2021). "Strong antitumor effects and the lower toxicity of anti-FGFR4 antibody suggests a general strategy for avoiding adverse events with FGFR4 inhibitors for liver cancer therapy." (PMID 32154250, 2020). "It was reported that beta-klotho, in partnership with FGFR4, induced cell apoptosis and inhibited cell proliferation in liver cancer." (PMID 32111983, 2020). "Particularly, FGFR4 expression was significantly upregulated in most liver cancer cases, and enhanced FGF19-FGFR4 signaling is linked to HCC progression, metastasis, and poor survival." (PMID 32154250, 2020). "It was reported that KLB in partnership with FGFR4 induced apoptosis and inhibited tumor cell proliferation in liver cancer, which was correlated with depression of the AKT and mTOR pathways." (PMID 31695781, 2019). "Overexpression of FGF19/FGFR4 significantly correlated with EpCAM as a marker of hepatic cancer stem cells within the fatty liver-steatosis-cirrhosis-HCC sequence." (PMID 27447573, 2016). "Overexpression of FGF19/FGFR4 significantly correlated with EpCAM as a marker of hepatic cancer stem cells within the fatty-steatosis-cirrhosis-HCC sequence." (PMID 27447573, 2016). "We also show that FGFR4 expression is elevated in several types of cancer, including liver cancer, as compared to normal tissues." (PMID 22615798, 2012). "Given the accumulating evidence for the participation of FGFR4 in liver tumorigenesis and HCC progression, we believe that a therapeutic intervention that includes an anti-FGFR4 neutralizing antibody is likely to be beneficial in the treatment of liver cancer." (PMID 22615798, 2012). "Together these data suggest a link between FGFR4, liver tumorigenesis, and liver cancer progression." (PMID 22615798, 2012). "We showed that in vivo, LD1 acts on liver cancer xenograft tumors by inhibiting the modulation of genes downstream from FGFR4 and by blocking tumor growth." (PMID 22615798, 2012).
liver cancer (continued). "LD1 inhibited: 1) FGF1 and FGF19 binding to FGFR4, 2) FGFR4–mediated signaling, colony formation, and proliferation in vitro, and 3) tumor growth in a preclinical model of liver cancer in vivo." (PMID 22615798, 2012). "To further validate this idea and to explore the putative utility of blocking EIF4A3 and FGFR4 simultaneously in liver cancer cells, we performed functional assays in response to EIF4A3‐silencing alone or in combination with a specific FGFR4‐inhibitor (BLU9931 or BLU)." (PMID 36419260, 2022). "Finally, we show that FGFR4 expression is elevated in several types of cancer, including liver cancer, as compared to normal tissues." (PMID 22615798, 2012). "Previous ChIP-sequencing from the ENCODE project in HepG2 cells, a liver cancer cell line that expresses HNF1A, and from our group in UM5 cells found an HNF1A binding peak, which contains the HNF1A binding sequence, in the FGFR4 enhancer region found in the first intron of the FGFR4 locus." (PMID 40731412, 2025). "Given that overexpression of FGFR4 significantly correlates with EpCAM, a marker of hepatic cancer stem cells, within the fatty liver-steatosis-cirrhosis-HCC sequence, FGFR4 may have the ability to regulate cancer stem cells and lead to chemoresistance in HCC or other cancers." (PMID 30634399, 2019). "Consequently, FGFR4 is a potential therapeutic target and its inhibition may provide a therapeutic benefit to liver cancer patients." (PMID 22615798, 2012). "This study also demonstrates that EIF4A3 can control tumourigenic capacity of liver cancer cells in vitro and the in vivo tumour growth in a preclinical HCC model of Hep3B‐induced xenografts by the alteration of the expression and splicing events of key oncogenes such as FGFR4." (PMID 36419260, 2022). "But more importantly, the pattern of increasing expression of FGF19, FGFR4 and EpCAM within the HCC, suggests a mechanistic interaction between the fibroblast growth factor/receptor and hepatic cancer stem cells, which has not been described prior to this study." (PMID 27447573, 2016).